ZNF846 (zinc finger protein 846)
Description:
May be involved in transcriptional regulation.
Synonyms: LOC100505555
Tractability: PROTAC: ubiquitination databases record sites on it.
Gene: Protein-coding gene on chromosome 19 (9,751,993 to 9,793,180, reverse strand). Ensembl gene ENSG00000196605.
Subcellular location: Nucleus
Subcellular location (Human Protein Atlas): Actin filaments
Gene Ontology:
Molecular function: protein binding; DNA-binding transcription factor activity, RNA polymerase II-specific; RNA polymerase II transcription regulatory region sequence-specific DNA binding
Biological process: regulation of transcription by RNA polymerase II; regulation of DNA-templated transcription
Cellular component: nucleus
Genetic constraint (gnomAD): Loss-of-function variants: 11 observed, 13.11 expected, observed/expected ratio (o/e) 0.84, 90% interval 0.53 to 1.39. The upper end of that interval is the gene's LOEUF score, 1.39, which puts it in group 5 of 6, group 1 being the genes least tolerant of losing a copy. Missense variants: 700 observed, 640.35 expected, observed/expected ratio (o/e) 1.09, 90% interval 1.03 to 1.16. Synonymous variants: 222 observed, 218.46 expected, observed/expected ratio (o/e) 1.02, 90% interval 0.91 to 1.14.
Homologues: Orthologues: chimpanzee ZNF846 (98% identical), macaque ZNF846 (92% identical), Drosophila melanogaster CG3281 (21% identical), Drosophila melanogaster Phs (20% identical), Drosophila melanogaster CG2712 (18% identical), dog ZNF846 (11% identical). Paralogues in human: ZNF266 (46% identical), ZNF778 (44% identical), ZFP90 (38% identical), ZNF582 (37% identical), ZNF560 (36% identical), ZNF599 (36% identical), ZNF77 (36% identical), ZNF555 (36% identical), ZNF404 (36% identical), ZFP37 (35% identical), ZNF805 (35% identical), ZNF20 (34% identical), and 50 more.
Diseases named in the same sentence as ZNF846 in open-access papers:
ZNF846 is named in the same sentence as 2 diseases in open-access papers, as found by Europe PMC text mining. Sharing a sentence is not in itself a finding about the gene and the disease. The quoted sentences say what the papers report.
cancer (1 paper, 2017). A tumor composed of atypical neoplastic, often pleomorphic cells that invade other tissues. "We detected insertion at the intronic region of RBM4 (chr11), known to be associated with cancer and ncRNA SMG1P5 (chr16), downstream of TINAGL1 (chr1) and LOC339807 (chr2) and at an intergenic region that is 30Kb upstream of ZNF846 and 11Kb downstream of FBXL12 in chromosome 19." (PMID 28410234, 2017).
ZNF846 also shares sentences with these, for which no sentence is quoted: tumor (1 paper).